IL6 (interleukin 6)
Diseases named in the same sentence as IL6 in open-access papers (continued):
Sharing a sentence is not in itself a finding about the gene and the disease.
Sepsis (continued). "Our findings indicate that cp‐OLA@MΦ NPs effectively neutralized key pro‐inflammatory cytokines such as TNF‐α, IL‐1β, and IL‐6, all of which are closely associated with the pathophysiology of sepsis." (PMID 39836501, 2025). "Elevated IL-6 levels are a hallmark of several syndromes characterized by dysregulated immune activation, including sepsis, CRS, and HLH." (PMID 41155261, 2025). "In light of this, the aim of this study was to explore the expression levels of serum HBP and IL-6, along with traditional indicators, and their diagnostic value in patients with severe pneumonia complicated with sepsis." (PMID 41293058, 2025). "In sepsis, high levels of proinflammatory cytokines (i.e., IL-6, IL-8, IL-18, and IL-1β) have been associated with higher mortality, a similar correlation in IE patients can be assumed." (PMID 41152385, 2025). "In PubMed and Google Scholar, the studies were searched out, which correlating to IL-6 related pathways and associating with the pathological process of sepsis." (PMID 39891057, 2025). "Enhanced levels of IL-6, a key mediator of inflammation which is commonly associated with the acute phase of sepsis, suggest its critical role in driving the systemic inflammatory response." (PMID 40510342, 2025). "A study assessing the diagnostic accuracy of the neutrophil CD64, PCT, and IL-6 for sepsis found that CD64 exhibited a sensitivity of 0.88 (95% CI, 0.81–0.92), a specificity of 0.88 (95% CI, 0.83–0.91), and an AUC of 0.94 (95% CI, 0.91–0.96)." (PMID 39201697, 2024). "Based on the definition of Sepsis-3, a combined biomarker approach that includes PCT, IL-6, pentraxin-3 and lactate showed promising results in predicting 28-day all-cause mortality in patients diagnosed with sepsis or septic shock." (PMID 38716051, 2024). "IL-6 is considered a biomarker with high diagnostic and prognostic value in sepsis, quickly rising to peak levels early in sepsis." (PMID 38835774, 2024). "This led to higher production of TNF-α and IL-6, resulting in increased susceptibility to sepsis induced by methicillin-resistant Staphylococcus aureus (MRSA) infection." (PMID 38678059, 2024). "Previous studies have demonstrated the inhibitory effect of insulin on the release of sepsis-associated cytokines, including IL-1, IL-6, and TNF-α." (PMID 39263577, 2024). "Early repetitive or chronic RIC administration has shown benefits in reducing levels of inflammatory cytokines (such as TNF-α, IL-1β, and IL-6) following lipopolysaccharide-induced sepsis and has been associated with a reduction in mortality in mice." (PMID 36445625, 2024). "An association between elevated IL-6 values and bad outcome, for example regarding mortality in patients with sepsis, was demonstrated in previous studies, which provides the rationale for the focus of the current study on IL-6." (PMID 38336628, 2024). "It is well known that increased IL-6 levels in sepsis patients are associated with increased mortality, and a study reported that decreasing IL-6 levels can reduce organ failure in sepsis patients." (PMID 38165570, 2024). "Increased cytokines like interleukin-6 (IL-6) activate the nuclear factor kappa B (NF-B) pathway, which causes sepsis, capillary damage, acute pulmonary injury, severe acute respiratory distress (ARDS), multi-organ damage, and death." (PMID 38389078, 2024). "Elevated levels of IL-6 have been reported in severe infections, such as sepsis and viral infections, and are associated with poor outcomes." (PMID 38251210, 2024). "In conclusion, hepatic HNF4α activity is decreased during sepsis, causing PPARα downregulation, metabolic problems, and a disturbed IL6-mediated acute phase response." (PMID 39261648, 2024). "Our nomogram, including CHD, LYMP, NLR, RDW, lactic acid, PT, CRP, PCT, Tbil, ALT, and IL6, exhibits good performance for predicting mortality risk in adult sepsis patients." (PMID 38765257, 2024).
Sepsis (continued). "Specifically, we report here that CLP-sepsis caused a significant increase in IL-1β, IL-6, CCL3, CLL4, CXCL1, CXCL10 and GM-CSF, all of which contribute to sepsis-induced cytokine storm and, hence, to cardiac and organ dysfunction." (PMID 39559354, 2024). "Measured at the time of sepsis suspicion, IL-6 levels were found to be associated with sepsis severity and mortality risk in preterm infants." (PMID 38671704, 2024). "It has also been found that IL-6 is associated with tissue hypoxia and cellular stress response and can precede clinical signs of sepsis, making it an important tool for the diagnosis of sepsis." (PMID 39371766, 2024). "During sepsis, IL-6 is produced in response to pathogenic stimuli, and IL-6R is generated by neutrophils." (PMID 39835102, 2024). "Serum concentrations of neutrophil gelatinase-associated lipid transport protein, IL-6, IL-8, IL-10 and resistin are high during severe sepsis." (PMID 38716051, 2024). "Cytokines and chemokines such as IL-6, IL-1ra, and IL-8 have been demonstrated to have diagnostic utility as early sepsis markers, while acute phase reactants such as CRP and PCT rise during the later phases of systemic inflammation." (PMID 38312920, 2024). "IL-10 and NEWS had the strongest association with sepsis development, whereas IL-6 and CRP had the strongest association with ICU admission and in-hospital mortality." (PMID 39212218, 2024). "There are also studies showing that gene polymorphism of the IL-6 locus has a greater impact on the prognosis of sepsis but has little impact on the pathogenesis of sepsis." (PMID 38848433, 2024). "The levels of procalcitonin and IL-6 decreased, suggesting a reduction in inflammation, while lactate levels, which are associated with tissue hypoxia and sepsis severity, also showed improvement." (PMID 39330895, 2024). "IL-6 is an acute phase-response biomarker associated with detrimental outcomes during sepsis and ARDS." (PMID 39407979, 2024). "IL-6 levels are also increased in a range of conditions involving inflammatory processes, including sepsis, neoplasms, autoimmune diseases, acquired immune deficiency syndrome (AIDS), alcoholic liver disease and infections or transplant rejection." (PMID 39589972, 2024). "Our predictive model, which included six indicators named CHD, NLR, RDW, lactic acid, PT and IL6, yielded good performance for predicting mortality risk in adult sepsis patients." (PMID 38765257, 2024). "Other studies have also reported similar results, showing an association between IL-6 and mortality in patients with sepsis, with a stronger association in those with septic shock." (PMID 39589972, 2024). "Conversely, men predominantly display Th1 responses and overproduce TNF-α, IL-1β, IL-2, IL-6, and IL-8, which in turn is often associated with poor outcomes, such as septicaemia and bacteremia." (PMID 37004108, 2023). "The fact that the half-life of IL-6 lies within minutes, suggests that once the causative trigger is eliminated, IL-6 levels should decrease rapidly, i.e., after surgery, remaining elevated only in cases of prolonged immune answer e.g., sepsis." (PMID 37711559, 2023). "IL-6 can be secreted by macrophages in response to pathogen-associated molecular patterns elevated in patients with sepsis, indicating that it is associated with the development of this condition." (PMID 37621924, 2023). "IL-6 is one of the major cytokines produced by endothelial cells and inflammatory cells in sepsis, cytokine release syndrome associated with chimeric-antigen receptor T-cell therapy, and cytokine storm syndrome after COVID-19 infection." (PMID 36622466, 2023). "Elevated concentrations of IL-6 trigger a detrimental cytokine storm in sepsis and are negatively associated with poor clinical outcomes." (PMID 36765040, 2023).
Sepsis (continued). "The A allele of rs2297630 was related to the increased production of interleukin 6, which was thought to be associated with not only the occurrence of sepsis but also with diabetes mellitus and diabetic retinopathy." (PMID 38075689, 2023). "High levels of IL-6 have been shown to be associated with an increased risk of severe sepsis and a higher mortality rate." (PMID 37388447, 2023). "In a recent study involving patients with sepsis, haemoadsorption was associated with improved haemodynamics, reduced IL-8 and IL-6 levels, and reduced ICU length of stay and mortality, compared to the controls." (PMID 36750878, 2023). "T lymphoneia associated with concomitantly elevated TNF and IL-6 in the serum at 12 hpi in LPS sepsis or CLP sepsis, among other pro-inflammatory cytokines and chemokines (PICC)." (PMID 37332010, 2023). "IL-6 positively correlated with CRP in our SIRS/sepsis cohort (r = 0.230, p = 0.006), and this association was still significant when the patients with liver cirrhosis were excluded (r = 0.298, p = 0.001)." (PMID 38139346, 2023). "A number of studies have shown that CRP, IL-6, and other markers have more diagnostic value in sepsis." (PMID 36691469, 2023). "Immune cell activation via LPS from the cell wall of infecting bacteria during sepsis can cause the production of inflammatory cytokines such as IL-6, IL-1β, and TNF-α." (PMID 37761018, 2023). "Reduced systemic Plg levels are associated with sepsis severity and correlate negatively with IL-6 levels." (PMID 36917195, 2023). "It has been reported that IL-6 was tightly associated with sepsis mortality and can be used as a predictor of sepsis severity due to its slow metabolism and easy detection." (PMID 37636994, 2023). "It was concluded that there was a higher morbidity and mortality rate from sepsis in men, and this seems to be associated with differences in respiratory tract infection frequency and IL-6 plasma levels, among the genders." (PMID 38152329, 2023). "The sepsis-associated elevation in neuroinflammatory mediators, such as IL-6 and MCP-1, were greatly reduced in the CNS by the ITK inhibitor." (PMID 37175808, 2023). "This protection was associated with a significant attenuation of sepsis-induced tissue injury and systemic accumulation of serval surrogate biomarkers [e.g., IL-6, Keratinocyte-derived Chemokine (KC), and Soluble Tumor Necrosis Factor Receptor I (sTNFRI)]." (PMID 37239992, 2023). "As such, during the COVID-19 pandemic, the role of IL-6 has been widely explored as a diagnostic tool, to assess early inflammation and the risk of sepsis, and to address therapeutic strategies." (PMID 37896877, 2023). "Pro-inflammatory cytokine IL-6 is well recognized as a biomarker for sepsis and sepsis-associated death." (PMID 36845137, 2023). "S100A8, MMP8, CSF3 and IL-6 protein levels in the peripheral blood of sepsis patients were revealed to be substantially associated with GCS scores following a correlation investigation of the four extracellular molecules with clinical indications (all p<0.05)." (PMID 37901226, 2023). "The aim of this study was to evaluate the change in the diagnostic procedure focusing on clinical signs of sepsis and the establishment of the infection parameter IL-6 in laboratory screening." (PMID 38255366, 2023). "Plasma concentrations of specific cytokines TNF-α, IL-1β, IL-6, and IL-8 are often elevated in patients with sepsis, and cytokine concentrations are associated with the severity and prognosis of sepsis." (PMID 36199375, 2022). "On the other hand, the C allele was found to be associated with sepsis, high levels of circulating IL-6, and mortality increase in dialyzed subjects." (PMID 35205271, 2022). "LPS-induced sepsis can cause the body to produce many inflammatory mediators (IL-1, IL-6, and TNF-α), resulting in a cascade of inflammatory responses that can cause extensive tissue and cell damage and damage to multiple organ structures." (PMID 35482440, 2022).
Sepsis (continued). "The measurements of CSA of myofibers and the muscle contractile properties suggested that the knockdown of PGC-1ɑ abolished the protective effects of IL-6 KO against sepsis-associated skeletal muscle atrophy." (PMID 35528525, 2022). "These capacities were essential when ECLipse was applied to identify sepsis in clinical plasma samples: Measuring multiple host factors (i.e., IL-3, IL-6, and PCT) led to high diagnostic accuracy (AUC = 0.93)." (PMID 36129990, 2022). "Proinflammatory cytokines, such as IL-6 and IL-1, are important in the early phase of systemic inflammation and have been associated with cognitive impairments in sepsis." (PMID 35488237, 2022). "Elevated cytokines—as interleukin-6 (IL-6)—activate the nuclear factor kappa B (NF-κB) pathway, which causes sepsis, capillary damage, acute pulmonary injury, severe acute respiratory distress (ARDS), multi-organ damage, and death." (PMID 35941669, 2022). "The immunoparalysis of DCs increases the levels of IL‐10 and transforming growth factor‐β, and decreases the levels of IL‐6, IL‐12p70 and costimulatory molecules, thus promoting the generation of Tregs and leading to sepsis‐associated immunosuppression." (PMID 36106559, 2022). "The reported studies revealed that interleukin-6 (IL-6) is a key modulator of the inflammatory response in the initial phase of sepsis, which is closely associated with organ failure." (PMID 35463642, 2022). "The production of IL-6, TNFα, IL-18, and IL-1 pro-inflammatory cytokines along with IL-10 (anti-inflammatory cytokine) is a hallmark response to sepsis." (PMID 36439175, 2022). "Initially, among them, C-reactive protein (CRP), procalcitonin (PCT), interleukin-6 (IL-6), have been postulated as diagnostic and prognostic biomarkers in sepsis, although with limitation." (PMID 36459524, 2022). "An increase in the level of TNF-α in the serum of patients with sepsis increases the risk of mortality; moreover, the level of IL-6 in the serum of patients with sepsis decreases, which helps patients with sepsis recover from the illness." (PMID 35370629, 2022). "The inflammatory cytokine response to an E. coli LPS challenge ex vivo was also much less in blood from sepsis patients than in control assays and this depressed LPS-evoked IL-6 production was associated with increased in-hospital mortality." (PMID 35981050, 2022). "In LPS-induced sepsis, the expression of pro-inflammatory markers, such as IL-6 and TNF-α, is associated with the degradation of the vascular endothelium glycocalyx." (PMID 35200650, 2022). "Together, these results suggested that we successfully established a murine model of sepsis-associated skeletal muscle atrophy, and the IL-6 KO attenuated CLP-induced skeletal muscle atrophy and subsequent contractile dysfunction." (PMID 35528525, 2022). "In patients with sepsis, IL-6 decreased levels were associated with ICU survival; NGAL levels rose in non-survivors, while HMGB-1 levels were unchanged in both survivors and non-survivors regardless of complications." (PMID 34991675, 2022). "TNF-α and IL-6 are critical pro-inflammatory cytokines in sepsis due to their consistent association with the severity, mortality and organ dysfunction of patients with sepsis." (PMID 35167625, 2022). "CRP and PCT have been largely studied as diagnostic markers in sepsis in both, children and adult populations, IL-6 have been studied in children and neonates." (PMID 35550043, 2022). "With the combined application of IL-6 and neutrophil-lymphocyte ratio as a predictive model, the predictive power of death risk in sepsis patients was significantly improved." (PMID 36452899, 2022). "Stratifying the changes in IL-6 evoked by LPS in assays from sepsis patients there was a significant association of decreased IL-6 concentrations with in-hospital mortality (p = 0.046)." (PMID 35981050, 2022).
Sepsis (continued). "To further investigate the pro-inflammatory effect of exosomal delivery had on monocytes, we analysed the production of two major inflammatory cytokines frequently associated with sepsis mortality: IL-6 and IL-10." (PMID 36061862, 2022). "The present study first found that IL-6 deficiency and the inhibition of IL-6 trans-signaling alleviated some sepsis-associated muscle atrophy and weakness." (PMID 35528525, 2022). "ADAMTS13 activity below 45% has already been associated with increased mortality in sepsis, activity below 30% with significantly higher systemic inflammation (i.e., IL-6 concentrations) and greater incidence of overt DIC." (PMID 35551628, 2022). "Reduced monocyte numbers and M/H ratios at the admission of neonates for suspected sepsis are associated with the development of septic shock, and these parameters were inversely correlated with inflammation markers, such as IL-6, IL-8 and IL-10." (PMID 36368184, 2022). "The up-regulation of TNF-α, IL-1β, and IL-6 has been confirmed to be inextricably associated with sepsis-elicited myocardial damage." (PMID 35599576, 2022). "MTA is an increasingly appreciated metabolic regulator of susceptibility and severity in sepsis; high plasma levels correlate strongly and positively with IL-6 and IL-8, and weakly with TNF-α, and signal a worse prognosis due to hyperinflammation." (PMID 35202243, 2022). "IL-6 is also implicated in the development of sepsis and IL-6 blockade has been shown to improve survival in a mouse model of sepsis." (PMID 36422559, 2022). "Although PCT, IL-6 and IP-10 levels were independently associated with sepsis diagnosis, diagnostic accuracy of clinical variables combinations was similar to combinations with biomarkers and superior to biomarkers alone." (PMID 36509812, 2022). "Sepsis‐mediated endothelial damage increases IL‐6 proliferation that causes soluble IL‐6 to bind to its receptor (IL‐6R), forming the IL‐6/IL‐6R complex." (PMID 33719215, 2021). "Several biomarkers are associated with the occurrence and development of sepsis, such as LPS, IL-6, and CRP." (PMID 34281552, 2021). "The δ sepsis phenotype with the highest mortality was associated with elevated serum lactate levels and IL-6 compared with other sepsis phenotypes, supporting that host inflammatory response is associated with clinical outcome." (PMID 33850271, 2021). "Studies in older pediatric patients and adults are in line with our findings; in these patients with sepsis, higher levels of IL-6 at the onset of sepsis are associated with a poorer outcome." (PMID 33407770, 2021). "The aim of our study was to integrate the results of clinical studies to compare the diagnostic accuracy of neutrophil CD64, PCT, and IL-6 for sepsis in adult patients by meta-analysis." (PMID 33902476, 2021). "Here we studied the kinetics of systemic neutrophil activation (HBP and MPO) and pro-inflammatory reaction (IL-6 and IL-8) in early sepsis in critically ill patients, using the emergence of the first sepsis-associated OD as a surrogate for the sepsis phase." (PMID 33461369, 2021). "Plasma concentrations of heparin-binding protein (HBP), myeloperoxidase (MPO), IL-6 and IL-8 appear to be correlated with emergence of the first sepsis-associated organ dysfunction." (PMID 34945111, 2021). "Collectively, NLR_IL-6 performed best in prediction, discrimination, and reclassification of the 28-day mortality risk in sepsis." (PMID 33796105, 2021). "Some studies have shown that indicators such as tumor necrosis factor-α (TNF-α), interleukin-6 (IL-6), and interleukin-10 (IL-10) are used as early biomarkers of sepsis-associated ARDS." (PMID 34095029, 2021). "Accordingly, the present study sought to develop a new death risk screening tool defined as NLR combined with IL-6, and the 28-day mortality predictive values of several biomarkers in sepsis were evaluated and compared." (PMID 33796105, 2021).